PDCD1LG2 (programmed cell death 1 ligand 2)
Diseases named in the same sentence as PDCD1LG2 in open-access papers (continued):
Sharing a sentence is not in itself a finding about the gene and the disease.
cancer (continued). "We found in this study that the CD274/PDCD1LG2 expression was correlated with TMB and MSI in some cancer types." (PMID 33833994, 2021). "In our cancer center patients with LIHC, the median serum CD274 and PDCD1LG2 level were 5.1 and 14.7 μg/μl, respectively." (PMID 33833994, 2021). "The present work illustrated a comprehensive workflow for a pan-cancer analysis and thoroughly investigated the role of CD274/PDCD1LG2 in gastrointestinal cancers." (PMID 33833994, 2021). "PRDM1 expression positively correlates with the expression of LAG3, CTLA4, PDCD1 (PD-1), CD274 (PD-L1), PDCD1LG2 (PD-L2), TIGIT in the majority of 33 cancer types." (PMID 33384601, 2020). "PD-L1 (B7-H1, CD274) and PD-L2 (PDCD1LG2, B7-DC, CD273) are immune co-signaling molecules belonging to the B7 family, and they are expressed in several cancer types and, also, in infiltrating immune cells." (PMID 33194598, 2020). "Generally, PRDM1 expression positively correlates with the expression of LAG3, CTLA4, PDCD1 (PD-1), CD274 (PD-L1), PDCD1LG2 (PD-L2), TIGIT in the majority of 33 cancer types." (PMID 33384601, 2020). "Recent studies have suggested that immune checkpoints play an important role in the immune escape of cancer, so we further analysed the relationship between the 4 subtypes and 8 immune checkpoint genes (PDCD1, CD274, PDCD1LG2, CTLA4, CD86, CD80 and CD267)." (PMID 31995855, 2020). "The scatter plot shows the relationship between the Th1 and Th2 scores and expression values of the three genes (CD274 (PD-L1), PDCD1LG2 (PD-L2), and PDCD1 (PD-1)) that were considered as cancer immunotherapy genes involved in the PD-L1/PD-1 axis." (PMID 29721184, 2018). "Additionally, it was reported that miR-19b-1 may also target caspase 8 (CASP8), death-associated protein kinase 3 (DAPK3), and programmed cell death 1 ligand 2 (PDCD1LG2), all genes known to be involved in apoptosis, further suggesting the anti-apoptotic function of the miR-17-92 cluster in cancer." (PMID 19440450, 2008). "Notably, genes such as HAVCR2, PDCD1LG2, CD274, and TIGIT exhibited the strongest positive correlations with STX7 across more than 20 cancer types, suggesting a role for STX7 in immune checkpoint-mediated regulation." (PMID 40999361, 2025). "Finally, we sought to confirm that INCR1 regulates components of the IFNγ-induced JAK/STAT pathway and the resulting expression of immune checkpoints IDO1, CD274, and PDCD1LG2 in human LUAD cells, as shown in other cancer types." (PMID 40449595, 2025). "Also, in most of the cancers, there was a significant correlation between UBE2C gene expression and CD96, CD274, CSF1R, KDR, and PDCD1LG2." (PMID 38577722, 2024). "Furthermore, positive correlations of PRC1 and some immune checkpoint genes (CD274, CTLA4, HAVCR2, LAG3, PDCD1, PDCD1LG2, TIGIT, and CD86) were observed in several cancers, especially BLCA, BRCA, KIRC, LUAD, LIHC, PRAD and THCA." (PMID 37563591, 2023). "Notably, in the PD-1/PD-L1 cancer immunotherapy pathway, CD274, the gene that transcribes PD-L1, PDCD1LG2, the gene that transcribes PD-L2, and PTPN11, the gene that encodes SHP2 are all predicted to be activated by IFNγ in astrocytes." (PMID 37828609, 2023). "In addition, we studied the relationship between the expression of KCC2 (SLC12A5) and NKCC1 (SLC12A2) in pan-cancer and immune checkpoint genes, including SIGLEC15, IDO1, CD274, HAVCR2, PDCD1, CTLA4, LAG3, and PDCD1LG2." (PMID 35372048, 2022). "Notably, in GBM cancer cells, CD274 (PD-L1), PDCD1LG2 (PD-L2), LGALS9 (Galectin-9), and PVR (CD155) were correlated with m6A regulators." (PMID 35558067, 2022). "In addition, CD274 and PDCD1LG2 expression has been observed to be sex-dependent in HNSC and some other cancer types." (PMID 36276934, 2022). "Besides, our research manifested the correlation of SLC7A11 with 8 IC genes, namely CD274 (also known as PD-L1), HAVCR2, LAG3, SIGLEC15, PDCD1LG2, CTLA4, PDCD1, and TIGIT in 33 cancer types." (PMID 36267158, 2022).
cancer (continued). "Our results revealed that in GBM cancer cells, expression of CD274 (PD-L1), PDCD1LG2 (PD-L2), LGALS9 (Galectin-9), and PVR (CD155) were positively correlated with the expression of multiple m6A regulators, especially YTHDF2, YTHDF3, LRPPRC, METTL3, RBM15B, FTO, and ALKBH5." (PMID 35558067, 2022). "We further explored the correlation between the expression of LIPT1 and eight immune checkpoints (PD-L1, CTLA4, HAVCR2, LAG3, PDCD1, PDCD1LG2, SIGLEC15, and TIGIT), and found that LIPT1 levels were correlated with the expressions of these immune checkpoints, especially PD-L1, in most cancer types." (PMID 35837286, 2022). "As a result, in all seven cancer types, CD274/PDCD1LG2 was correlated with at least one DNMT gene." (PMID 33833994, 2021). "In all seven cancer types, CD274/PDCD1LG2 was correlated with at least one MMR gene." (PMID 33833994, 2021). "For instance, the expression of CD27, CTLA4, PDCD1LG2; TNFRSF18 were all significantly inhibited across different types of TCGA cancers as can be seen in the comprehensive study of more than 10,000 tumors comprising 33 diverse cancer types by utilizing data compiled by TCGA92." (PMID 31358815, 2019). "Third, CD274 and PDCD1LG2 were deleted in some cases of TCGA NSCLC and CCLC cancer cell lines." (PMID 28977839, 2017). "The study found a negative correlation among STAAD cancer patients between NPRL2 expression and PDCD1LG2, LAIR1, and BTLA checkpoint markers." (PMID 39932765, 2025). "Additionally, a strong negative correlation was observed between the expression of pdcd1lg2 and the infiltration of MDSC in all almost kinds of cancers." (PMID 37006239, 2023). "Notably, transcripts for PD-1 (Pdcd1) were observed only in T cell clusters whereas PD-L1 (Cd274) transcripts were more abundant in neutrophils, DCs and macrophages and PD-L2 (Pdcd1lg2) in DCs and not in EGFR+ cancer cells." (PMID 35624211, 2022).
infection (71 papers, 2010 to 2026). The state of being infected such as from the introduction of a foreign agent such as serum, vaccine, antigenic substance or organism. "In N87p cells treated with TRAS-, HV-HP infection further induced PDCD1LG2 expression." (PMID 40642068, 2025).
adenocarcinoma (9 papers, 2019 to 2024). A common cancer characterized by the presence of malignant glandular cells. "In fact, we found that patients with adenocarcinoma harboring somatic mutations of EGFR, CTLA4, PDCD1LG2, or ZEB2 that only underwent surgical treatment and developed brain metastases may have the worst prognosis." (PMID 36629526, 2023). "Immune checkpoint blockade (ICB) gene analysis further revealed significant upregulation of LAG3, PDCD1, PDCD1LG2, HAVCR2, and CD274 in the solid pattern adenocarcinomas." (PMID 38505588, 2024).
gastrointestinal tumors (2 papers, 2013 to 2021). "Our study helps to understand the vital roles of CD274/PDCD1LG2 in gastrointestinal tumor-immune interactions." (PMID 33833994, 2021). "In this regard, taking advantage of the large data sets from TCGA, this study aimed to examine the expression profiles of CD274/PDCD1LG2 and the prognostic significance in human gastrointestinal tumors." (PMID 33833994, 2021).
PDCD1LG2 also shares sentences with these, for which no sentence is quoted: renal cell carcinoma (20 papers); pancreatic cancer (19); asthma (17); viral infection (16); autoimmune disease (15); diffuse large B-cell lymphoma (15); leukemia (13); helminth infections (12); triple-negative breast carcinoma (12); B-cell lymphoma (11); prostate carcinoma (11); head and neck cancer (10); metastatic disease (10); sarcoma (10); allergic disease (9); clear cell renal cell carcinoma (9); lung squamous cell carcinoma (9); malaria (9); pneumonitis (9); breast tumors (8); classical Hodgkin lymphoma (8); hematologic malignancies (8); myelodysplastic syndrome (8); myeloma (8); esophageal adenocarcinoma (7); esophageal squamous cell carcinoma (7); gastric adenocarcinoma (7); meningioma (7); pancreatic ductal adenocarcinoma (7); primary central nervous system lymphoma (7).
A further 229 diseases each share a sentence with PDCD1LG2 in 6 papers or fewer.